IFNG (interferon gamma)
Diseases named in the same sentence as IFNG in open-access papers (continued):
Sharing a sentence is not in itself a finding about the gene and the disease.
Arthritis (continued). "Significantly reduced arthritis scores, antibody response to type-2 collagen, and interferon-gamma levels were observed compared to controls (all parameters P < 0.05)." (PMID 22548124, 2012). "The results demonstrated that IL-17 was the first cytokine to peak (at 12 hours after arthritis induction), followed by IL-6, TNFα, IL-1β, and IFNγ at 24 hours after the challenge." (PMID 22676339, 2012). "Taken together these data demonstrate an early increase in systemic inflammation in mice with arthritis treated with MSCs which is mediated predominantly through IFNγ, IL-1β and IL-17." (PMID 22812502, 2012). "Using intracellular cytokine staining it was demonstrated that the IL-10-/- B cell mice with arthritis had an increased CD4+ IFNγ producing population." (PMID 22315945, 2012). "IFNγ also appears to play a role in regulating the IL-17 response; studies using murine arthritis models have demonstrated that IFNγ suppresses IL-17 production and regulates the outcome of a Th1 vs Th17 response." (PMID 21699708, 2011). "In line with this, the frequency of IFNγ-producing CII-specific T cells among CD4+ T cells also peaked before onset of clinical arthritis and subsequently declined with progression of disease." (PMID 20682070, 2010). "It is now clear that some experimental arthritis models are dependent on Th1/IFNγ, whilst others are Th17/IL-17 dependent or switch from TNFα dependency to a Th17/IL-17 profile in later stages of disease." (PMID 20824142, 2010). "Several lines of evidence have suggested that arthritis in mouse models is mediated through production of IL-17 by Th17 cells and is negatively regulated by the presence of IFNγ." (PMID 19706160, 2009). "In our study, we observed that IFNγ producing T cells co-expressed multiple genes of inflammatory molecules and SF Th1/Tc1 cells were enriched in SF compared to matching PB Th1/Tc1 cells in arthritis-irAE." (PMID 35413951, 2022). "Together, our NK, NK T, and T cell subcluster analyses revealed that IFNγ-producing Th1/Tc1 cells might play a critical role in the pathogenesis of arthritis-irAE." (PMID 35413951, 2022). "Furthermore, the role of IFNγ in animal models of RA remains controversial as it is shown to be protective in the collagen-induced model but required for arthritis development when induced by glucose-6-phosphate isomerase." (PMID 34478449, 2021). "Arthritis is an autoimmune condition exacerbated by IFNγ as well as IL-17 production by Th17 cells." (PMID 33348708, 2020). "Increased IL-10 production was correlated with decreased IFNγ cytokine production suggesting that these HSP70 may have potential to reduce disease severity in arthritis patients." (PMID 33348708, 2020). "Application of sCD83 not only reduced the clinical symptoms of arthritis, but also inhibited the antigen-specific T cell proliferation upon mBSA-restimulation and impaired production of key inflammatory effectors, including IL-17A, TNFα, IFNγ, and IL-6." (PMID 31001257, 2019). "Supporting the anti-inflammatory role of PRL in arthritis, PRL-receptor-null mice exhibited increased joint swelling and higher joint expression of the genes encoding for TNFα, IL-1β, IL-6, IFNγ, IL-17A, IL-21, IL-22, IL-23, and IL-10 when subjected to monoarticular AIA (MAIA)." (PMID 28506283, 2017). "In addition, IFNγ knockout mice upregulate IL-1β and accelerate collagen-induced arthritis in a mouse strain resistant to developing arthritis when sensitized with collagen." (PMID 28954232, 2017). "This is in contrast to arthritis-susceptible B6 IL10−/− mice, where previously published data show that in addition to upregulation in IL-1β, IL-6, Cxcl1 and Cxcl2, IFNγ and Cxcl10 are upregulated 16-fold and 141-fold at 2 weeks, and 22-fold and 189-fold at 4 weeks, respectively." (PMID 24967703, 2014).
Arthritis (continued). "Interestingly, they found that expression of TWIST1 in Th1 lymphocytes limited the expression of the cytokines interferon-gamma (IFNγ), IL-2, and TNFα, and ameliorated Th1-mediated immunopathology in delayed-type hypersensitivity and antigen-induced arthritis." (PMID 25238494, 2014). "Furthermore, B6 IL10−/− mice, a model for Th1-mediated arthritis, have a very pronounced IFNγ signature beginning at 14 days post-infection that persists for several weeks." (PMID 24967703, 2014). "Another possible mechanism by which statins may affect arthritis is through their induction of caspase-1, IL-1β, and IL-18 in monocytes, resulting in increased IFNγ production by T cells." (PMID 22537858, 2012). "The resulting IFNγ induction that in itself reduces arthritis may be counteracted by the T-helper type 2 skewing effect of statins." (PMID 22537858, 2012). "In addition, joint levels of TGFβ1, IL-10, IFNγ, IL-4 and IL-17 mRNAs were augmented in WT mice with arthritis." (PMID 22438945, 2012). "Indeed, stratification of CII-specific T cells showed that both B22a1+ and B22a1- T cells mounted an IFNγ and IL-2 response that was maintained in the draining lymph node from day 10 post immunization and throughout the development of clinical arthritis." (PMID 20682070, 2010). "In addition, stimulating PBMCs with the immunopromoting epitope in the presence of the immunoregulatory epitope reduced IL-17 and IFNγ production, and introducing the immunoregulatory peptide orally in a collagen induced arthritis model led to increased IL-10 and T regulatory cells." (PMID 30978945, 2019). "Furthermore, these data suggest that the molecular pathways IL-23/17 and IL 12/IFNγ may represent particular subtypes of arthritis determined by the tissue site of self-antigen exposure." (PMID 25253467, 2014). "Increased IFNγ production may, on the contrary, reduce arthritis." (PMID 22537858, 2012). "SLE patients treated with prednisolone showed higher serum levels of IFNγ than healthy controls, which were higher in SLE patients with fever, rash, arthritis, and LN." (PMID 38164134, 2023). "The frequency of IFNγ+ CD4+ T cells and Th1 cells was significantly decreased after treatment for arthritis-irAE, whereas the frequency of IL-17+ CD4+ T cells, t-Th17 cells, and Th17 cells was unchanged after treatment." (PMID 35413951, 2022). "Although IL17 has been highly studied due to its predominance in animal models of arthritis, both IL17 and IFNγ are involved in RA." (PMID 34080972, 2021). "An increase in the expression of FSTL1 induces arthritis and suppresses the production of chemokine-10 (CXCL10) and interferon-gamma (IFN-γ) in arthritic joints." (PMID 33776572, 2021). "For example, although antibody response plays an essential role in resolution of arthritis, greater roles of CD4+ T cells and iNKT cells as sources of IFNγ are reported in protection and resolution of Lyme carditis." (PMID 24967703, 2014). "Reduction of arthritis scores and spleen and thymus indexes was also observed, as well as the suppression of serum levels of TNF-α, IL-1β, IL-6 and interferon gamma (IFN-γ), which could be attributed to the downregulation of inflammatory mediators." (PMID 37511889, 2023). "Moreover, with the discovery of the newly identified Th17.1 cells, which express TBX21 and produce IFNγ but are also RORC positive, the potential role for IFNγ-producing Th1 cells in arthritis needs to be reconsidered." (PMID 34082814, 2021). "Similarly, AhR deficiency restricted to B cells impairs IL-10+CD19+CD21hiCD24hiBreg differentiation and function, resulting in an increase of IFNγ and IL-17-expressing CD4+ T cells, a decrease in Tregs, and the development of an exacerbated arthritis." (PMID 31722204, 2019). "PG-induced arthritis that was already attenuated by the absence of IFNγ was effectively prevented by anti-IL-17." (PMID 22269151, 2012).
Arthritis (continued). "In summary, the anti-CII antibody, IL-2, IL-17, and IFNγ data do not provide a possible mechanism for the accelerated arthritis observed in this study." (PMID 22537858, 2012). "Antigen-specific activation of naive TCR-Tg T cells lacking IFNγ in culture resulted in enhanced cytokine levels of IL-17A, which correlated with worsened uveitis but not arthritis in PG-immunized mice." (PMID 22269151, 2012). "Since atorvastatin was shown to inhibit IFNγ production, and absence of IFNγ signaling resulted in accelerated arthritis onset, reduced production of this cytokine may be a possible mechanism underlying accelerated arthritis onset due to atorvastatin treatment." (PMID 22537858, 2012). "The residual arthritis ensuing in the absence of IFNγ was further reduced by anti-IL-17 neutralization." (PMID 22269151, 2012). "Results obtained in a mouse model of spontaneous arthritis showing that TLR2 stimulation has been significant for the functioning of Tregs and the regulation of IFNγ–producing Th1 cells imply that the beneficial impact on IBDs might rely, at least partially, on the rBanLec-TLR2 interaction." (PMID 40305159, 2025). "Proportions of IFNγ+ IL-17− CD4+ T (Th1) cells were similar between the two groups, whereas IFNγ− IL-17+ CD4+ T (Th17) cells were enriched in the combined ICI arthritis group (% within CD4+ T cells; PD-1 inhibitor arthritis vs. combined ICI arthritis; 0.79 ± 0.83 vs. 1.89 ± 0.64; P = 0.04)." (PMID 35413951, 2022). "The patterns of inflammatory cytokine concentrations in serum are reported to differ from arthritis and paw swelling scores in CIA mice, which may be attributed to the potential involvement of other factors in improving pro-inflammatory IFNγ or IL6 levels in blood." (PMID 32549254, 2020). "Interestingly, we observed increased frequencies of Th1 (CD4+IFNγ+) and Th17 (CD4+IL-17+) cells in the small intestine and colon of CIA mice during the initiation phase of arthritis." (PMID 32332732, 2020). "The consequences of Th17 plasticity in arthritis were initially unclear, as the switch from IL-17 to IFNγ seemed unlikely to drive significant pathology given that administration of recombinant IFNγ to patients with rheumatoid arthritis has no adverse consequences." (PMID 24692225, 2014). "However, there is a precedent for IFNγ regulating the dependency of IL-17 in arthritis, and we demonstrate here that the arthritis ensuing in the absence of IFNγ in TCR-Tg mice is mediated by IL-17." (PMID 22269151, 2012). "Similarly, in a mouse model of IBD, IFNγ has been shown to suppress IL-23, and collagen-induced arthritis is induced in the absence of IFNγ signaling." (PMID 22423982, 2012). "In mice with experimental arthritis, interferon-gamma (IFN-γ) from B cells is found to inhibit Tregs, and the absence of B-cell-derived IFN-γ facilitates the transformation of CD4+ T cells into Tregs." (PMID 36211467, 2022). "Granzyme A (rather than IFNγ) from differentiated NK cells and CD4 T cells thus appears to be an important driver of CHIKV arthritis, with granzyme A dispensable for control of CHIKV infection." (PMID 28207896, 2017). "Compared to wild-type, IFNγ−/−, or IL-17−/− mice, severity and onset of arthritis were significantly reduced in the double knockout mice, suggesting that PGIA “became” IL-17-dependent in the absence of IFNγ." (PMID 26903711, 2016). "As might be expected, key pro-inflammatory cytokine USRs such as TNF, IFNG, IL6, and IL1B that were upregulated during CHIKV arthritis were downregulated (negative z-scores) in the ameliorated foot swelling seen in Gzma-/- mice." (PMID 35119362, 2022). "Interestingly, we found predominance of Mφs with a phenotype similar to GM-CSF- and LPS + IFNγ-stimulated Mφs (i.e., FRβ−/lo and non-overlapping expression of CD39 and CD73) in arthritis-affected joints in both humans and mice." (PMID 29780382, 2018).
Arthritis (continued). "Interestingly, the balance of serum IL-17A/IFNγ showed a trend to be increased (P = 0.09) at D44 if P. gingivalis oral infection was present in mice developing arthritis in the CFA/CII group compared with CFA/CII alone, and a nonsignificant trend in IL-17F/IFNγ ratios." (PMID 24456966, 2013).
glioma (264 papers, 2003 to 2026). A benign or malignant brain and spinal cord tumor that arises from glial cells (astrocytes, oligodendrocytes, ependymal cells). "Single-cell RNA sequencing of G34R mutant gliomas reveals upregulation of pathways associated with interferon-gamma (IFN-γ) signaling, JAK/STAT activation, and immune cell recruitment." (PMID 40813437, 2025). "IFNGR2, the receptor for interferon-gamma, plays a dual role in immune response modulation and is associated with the polarization of microglia and macrophages within the glioma microenvironment, influencing immunogenicity and the efficacy of immunotherapies." (PMID 38137116, 2023). "Additionally, co-expression analysis and functional enrichment analysis indicate that genes co-expressed with COPZ2 in glioma are predominantly associated with neutrophil-mediated immunity, granulocyte activation, and response to interferon-gamma." (PMID 39144445, 2024). "In addition, the GSVA revealed that epithelial-mesenchymal transition, IL6-JAK-STAT3 signaling, IL2-STAT5 signaling, interferon-gamma response, allograft rejection, and coagulation Hallmark gene sets were expressed at a higher level in cluster 2 gliomas of both IDH subtypes." (PMID 36970537, 2023). "In tumor cells, interferon gamma (IFN-g-), which responds to an antitumor immune activity, is a major regulator of PD-L1; PD-L1 expression in tumors can also be activated by oncogenic mutations, such as the deletion of phosphatase and tensin homologue in gliomas." (PMID 36313683, 2022). "γδ T cells are a rare subset of T cells with the potential to exert anti-tumor functions in an MHC-independent manner through IFNγ, perforin, and granzyme B release, with anti-glioma activity demonstrated in vitro and in vivo." (PMID 40095115, 2025). "Instead, glioma-secreted factors such as granulocyte–macrophage colony-stimulating factor (GM-CSF) and interferon-gamma (IFN-γ) sustained TAM viability despite CSF-1R blockade." (PMID 40867316, 2025). "Various inflammatory cytokines, including TNF, CSF2, IL1A, IL17A, IL6, and IFNG, were predictively inhibited in glioma samples exhibiting high CSMD1 expression." (PMID 38561856, 2024). "CD133+ glioma cells have been shown to lack MHC-I expression that can be restored following incubation with IFNγ." (PMID 39409895, 2024). "A co-culture system with CD8+ T cells and glioma cells decreased the proliferation of AP-2α-overexpressing U87 cells, but increased Ki67 expression and cytokines TNFα and IFNγ secretion, decreased PD-1 levels in CD8+ T cells in vitro." (PMID 37330579, 2023). "In fact, the NK cells can modulate the growth of the glioma via sensing growth factors and secreting interferon gamma and tumor necrosis factor alpha." (PMID 35668574, 2023). "As expected, the IFNGR score well represents the IFNG-related biological processes and extensively correlates with clinicopathological parameters that indicate a poor prognosis of glioma." (PMID 35492352, 2022). "For instance, IFNγ stabilises Irf8 activation in glioma cells and microglial C5/C5a complement component induced TMZ resistance." (PMID 36555253, 2022). "The DEGs were enriched in some Glioma-related processes, including “regulation of ion transport”, “interferon-gamma signaling”, and “interleukin-4 and interleukin-13 signaling”." (PMID 36138874, 2022). "As compared to the normal brain tissues, the genes with decreased copy numbers, such as IFNA1, IFNB1, and IFNG, had lower expression levels in glioma." (PMID 36428756, 2022). "For example, the expression level of interferon-gamma was positively correlated with PD-L1 in Glioma." (PMID 36138874, 2022). "For genes in interferon-gamma response, we confirmed that they are associated with ANXA1 expression, and show the differential expressed patterns in glioma subtypes grouped by ANXA1 expression." (PMID 34912807, 2021).
glioma (continued). "have recently reported upregulation of Arid5a in glioma is positively correlated with inflammation, immune response, IFNγ-mediated signaling, and apoptosis which affect the proliferation and growth of cancer cells." (PMID 35126382, 2021). "Administration of Ad-RTS-hIL12 to glioma patients also revealed pseudo-progression with increased frequencies of tumor infiltrating lymphocytes (TILs) producing IFNγ and expressing PD1." (PMID 33790740, 2021). "For example, infiltration of NKp44+ NK cells is present in many types of gliomas and positively correlates with the expression of pro-inflammatory NK cell cytokine genes, such as IFNG and TNF." (PMID 34925438, 2021). "The results showed up to 100-fold higher IFNγ+ T cell responses and eradicated 30% of gliomas, compared with soluble vaccine + anti-PD-L1 treatment." (PMID 34168976, 2021). "In animal models, exogenous IFNG induces glioma regression, and the anti-tumor effects of IFNG can be reinforced through inhibition of inducible nitric oxide synthase." (PMID 34566988, 2021). "Treatment with IFNγ and TNFα resulted in iNOS expression in glioma cells, which was mediated by p38 MAPK." (PMID 32467752, 2020). "We observed that splenocytes derived from glioma-bearing mice treated with Delta24-RGD produced IFNγ upon recognition of the glioma antigens." (PMID 32642679, 2020). "This combined viro-immunotherapeutic approach synergizes to overcome adaptive immune resistance induced by intratumoral PD-1 expressing CD8+ T cells, leading to an effective IFNγ-mediated antitumor immune response and long-term cure of glioma-bearing mice." (PMID 32642679, 2020). "In our experiments, we measured mRNA content of microglia released LPS/IFNγ-MV, but we cannot exclude additional transfer elements (such as membrane or signal proteins) from MV to glioma and TAM, responsible for the antitumor effects." (PMID 30853898, 2019). "In vivo, LPS/IFNγ-MVs injected in the brain of mice with glioma reduced the anti-inflammatory phenotype of TAMs and significantly reduced tumor size and tumor induced neurotoxicity." (PMID 30853898, 2019). "The present study demonstrated that microglia-derived LPS/IFNγ-MV transfer a protective-antitumor phenotype to the brain of glioma bearing mice." (PMID 30853898, 2019). "When MV, isolated from microglia stimulated with LPS/IFNγ were brain injected in glioma-bearing mice, we observed a phenotype switch of tumor associated myeloid cells (TAMs) and a reduction of tumor size." (PMID 30853898, 2019). "CXCL9 and CXCL10 were enhanced both at the RNA and protein level in glioma cells treated with IFNg and GSK126 compared to vehicle treatment." (PMID 30400835, 2018). "Gene expression of CXCL9 and 10 by qRT-PCR was determined in human and murine gliomas cell lines after treatment with a combination of IFNg and GSK126." (PMID 30400835, 2018). "We next developed another trans-suppression co-culture system using the human glioma tumor cell line LN-18 cells whose PDL1 cell surface expression can be upregulated by exogenous IFNγ treatment." (PMID 28325288, 2017). "In several early attempts, in situ delivery of interferon-gamma (IFN-γ) by viral vectors was applied to enforce the MHC class II expression in glioma cells and enhance the anti-tumor activity of T cells." (PMID 27835581, 2016). "The effect of rapamycin and interferon-gamma in 5'UTR-regulating TRPV1 translation was determined by western blot analysis in glioma cell lines." (PMID 27829230, 2016). "The therapy stimulated the clonal expansion of glioma antigen specific T cells in tumor bearing mice, with a significantly higher proportion of T cell precursors releasing IFNγ in response to glioma antigen." (PMID 25411122, 2014). "The CM from activated C6 glioma cells were generated following a more complex protocol (see the Method section), aimed to remove LPS and IFNγ from the media in order to avoid their direct effects on microglia." (PMID 24689533, 2014).